CD44 (CD44 molecule (IN blood group))
Diseases named in the same sentence as CD44 in open-access papers (continued):
Sharing a sentence is not in itself a finding about the gene and the disease.
cancer (continued). "CD44 shows alternative splice variants that play a role in cancer development and progression." (PMID 40342488, 2025). "Mechanistically, SPP1+ TAMs interact with cancer-associated fibroblasts (CAFs) at the invasive margins via SPP1–integrin/CD44 signaling, driving CAF activation, ECM deposition, and chemokine release, which establishes a stromal barrier that excludes CD8+ T cells and promotes ICB resistance." (PMID 41225975, 2025). "Magnetic stimulations at a moderate strength can inhibit cancer cell migration and stemness by upregulating genes associated with oxidative stress, including hyaluronan receptor (CD44), SRY-box transcription factor 2 (Sox2), and cell myc proto-oncogene protein (C-myc)." (PMID 39817348, 2025). "Furthermore CD44, encoding a cell-surface glycoprotein that drives inflammation and cancer progression, was recently identified as a key gene for the diagnosis and early detection of open neural tube defects." (PMID 40223808, 2025). "Various CD44 variants (CD44v), derived from ribonucleic acid (RNA) splicing of the standard CD44 isoform (CD44s), exist in different combinations and expression levels across various types of cancers." (PMID 40888184, 2025). "Through alternative splicing, CD44 can form isoforms with the inclusion of only standard exons, typical for normal tissue, or with the addition of variant exons, frequently expressed in cancer tissue and associated with chemoresistance." (PMID 40114966, 2025). "Similarly, in ovarian cancer, transforming growth factor β (TGFβ)–activated cancer-associated mesothelial (CAM) cells enhance stemness via CD44 activation." (PMID 41373619, 2025). "In conclusion, this comparative cross-sectional study demonstrates that the highest expression levels of the cancer stem cell marker CD44 and cytoplasmic VDR are significantly associated with aggressive histological types of EOT, particularly in patients with HGSC in FIGO stages III or IV." (PMID 40332380, 2025). "Additionally, our IMC data suggested that CD44 and YAP reciprocally regulate in cancer cells and that CD44 expression and YAP expression are associated with PD-L1 expression and CAF density in cancer regions." (PMID 39946200, 2025). "Besides, we also found that only CD276 was positively associated with UBA1 in most cancers, however, there are many other immune checkpoints like CD44, CD86 and CD274 illustrating a positive correlation with UBA6." (PMID 40046044, 2025). "The present study aimed to evaluate the immunohistochemical expression of differentiated embryonic chondrocyte 1 (DEC1), a marker of dysplasia severity, and cluster of differentiation 44 (CD44), which is associated with cancer progression, in OPMD and OSCC tissues." (PMID 40005368, 2025). "A high CD44/CD24 ratio is also linked to the ability of cancer cells to metastasize." (PMID 40227834, 2025). "Additionally, IL-6 and IL-8, produced by cancer cells in an autocrine manner, induce a fibroblastoid morphology and are associated with increased CD44 expression and enhanced self-renewal capacity." (PMID 41373619, 2025). "Elevated levels of CD44 expression have been associated with MDR in various cancers, including TCs." (PMID 40363706, 2025). "CD44 overexpression has been linked to cancer cell stemness, invasion, and metastasis." (PMID 39453005, 2024). "The exact role of different CD44 variants in cancer is still not well understood." (PMID 38672650, 2024). "CD44 genetic variants have been found to be related to various cancers." (PMID 38903932, 2024).
cancer (continued). "In addition, we revealed that the presence of Mott cells was inversely associated with cancer stem cell markers such as CD44 or tyrosine kinase molecules such as EGFR." (PMID 38337351, 2024). "In malignant tumors, abnormal CD44 expression is linked to aggressive growth and metastasis." (PMID 39184916, 2024). "The multiple effects of HIF may associated with the type of cancers, which expressing different interacting factors affected by CD44." (PMID 38783892, 2024). "CD44 (Cluster of differentiation 44) is a transmembrane glycoprotein encoded by the CD44 gene that contributes to the maintenance of cell proliferation, differentiation, and survival and has been associated with the aggressiveness of several human cancers." (PMID 39858584, 2024). "The expression of CD44 is associated with stemness in cancer cells and activation in immune cells." (PMID 38783892, 2024). "The overexpression of CD44 was linked to tumorigenic mechanisms, such as cell proliferation, metastasis, and migration, and to traits characterized in cancer stem cells such as epithelial–mesenchymal transition, self-renewal, and resistance to chemotherapeutics." (PMID 38931956, 2024). "Additionally, CD44, a transmembrane glycoprotein associated with cancer stemness, exhibited a significant induction in its expression level upon CML treatment." (PMID 38250151, 2024). "According to some researchers, CD44 variants were also considered promising cancer biomarkers." (PMID 38609981, 2024). "CD44 is excessively produced in various cell types, including cancer stem cells, and often exhibits alternative splicing variants believed to contribute to the development and progression of cancer." (PMID 39338413, 2024). "CD44 is a protein which is known to be strongly associated with cancer progression." (PMID 38539529, 2024). "The SPP1/CD44 axis has been linked to cancer chemoresistance in solid tumors, and it may represent a critical mechanism for cell-to-cell communication between cancer cells and TAMs53,54." (PMID 38521868, 2024). "Interestingly, CD44 and co-receptors in general have been rarely described as being mutated or aberrantly expressed in cancer, adding the advantage of target stability." (PMID 38761292, 2024). "Furthermore, PFKFB3 regulates cancer stemness in small cell lung cancer via the Hippo pathway, and its inhibition affects cancer stemness markers like CD44, associated with chemotherapy resistance." (PMID 39010066, 2024). "CD44, a biomarker of cancer stem cells, is associated with an unfavourable prognosis." (PMID 38606479, 2024). "We also observed that IGF2BP3 could enhance the expression of CD44, which is a well-known biomarker of cancer stem cells that are typically associated with increased proliferation capacity." (PMID 38504159, 2024). "Inhibition of CD44 has also been associated with enhanced chemosensitivity of cancer cells." (PMID 38542115, 2024). "The regulation functions of CD44 in cancers‐associated signaling pathways is summarized." (PMID 38783892, 2024). "Isoforms of CD44 were reported to play a crucial role in causing the EMT in cancer cells." (PMID 37835592, 2023). "Moreover, CD44 is associated with regulating essential signaling pathways that modulate invasion, proliferation, metastasis, and therapy resistance in cancer cells." (PMID 37886001, 2023). "Notably, the high expression of CD44 variants in cancer cells has been associated with increased binding and internalization of HA-based nanomaterials." (PMID 38140012, 2023). "Increased CD44 expression is associated with poor prognosis, cancer progression, and metastasis." (PMID 37664387, 2023). "Moreover, nearly all livers isolated from 48-week-old Cd44+/+;Nf2flox/flox;Alb-Cre mice were positive for expression of exon v3-, v6-, and v7-bearing CD44 variant isoforms that have previously been implicated in cancer." (PMID 37174657, 2023).
cancer (continued). "Higher levels of CD163, CD14, Fibronectin, B7-H3, LAG3, Tim-3, PD-L1, VISTA, CD25, and CD44 associated with fibroblasts, myeloid-derived cells, T cells, and NK cells were found in the ‘surrounding stromal leukocytes’ cf. ‘immune-rich cancer cell islet’ regions." (PMID 37046826, 2023). "Moreover, molecular modeling studies using PyRx revealed that 4a, among all SOXs, was found to be the best inhibitor of distinct biomarkers associated with cancer progression, i.e., human CD-44, EGFR, AKR1D1, and HER-2." (PMID 37108498, 2023). "CD44 is a cancer stem cell marker associated with cell aggregation, proliferation and migration." (PMID 36979661, 2023). "In addition, CD44, a marker of cancer stem cells, is also associated with iron homeostasis and immune infiltration, as shown in previous studies." (PMID 37240436, 2023). "Notably, several CD44 variants participate in reducing ROS levels in cancer cells by coupling with the glutamate-cystine transporter xCT." (PMID 37107200, 2023). "Therefore, development of anti-CD44 mAbs, which recognize each variant, is important for the further characterization of CSCs in various cancers." (PMID 37185762, 2023). "To date, most CD44 research has focused on its involvement in cancer-associated signalling." (PMID 37684253, 2023). "In addition, CD44 HA receptor variants can couple with glutamate-cystine transporter xCT and reduce the intracellular ROS in cancer cells, making them resistant to chemo- and radiotherapy." (PMID 37107200, 2023). "Furthermore, CD44 expression has been associated to the process of Epithelial to Mesenchymal Transition and is a typical receptor of cancer stem cells." (PMID 37398648, 2023). "CD44 is a stem cell-associated marker in various types of cancer." (PMID 37627119, 2023). "However, CD44 is upregulated in a variety of cancers and alternatively spliced variant isoforms (e.g. CD44v6) are mostly expressed in tumors, particularly in advanced stages." (PMID 37398648, 2023). "Moreover, CD44 is a receptor for HA, which is also found to be overexpressed in most cancer cells and associated with cancer progression." (PMID 37111653, 2023). "We identified the overexpression of vascular endothelial growth factor-α (VEGFA)/β-catenin/matrix metalloproteinase (MMP)-7/Cluster of Differentiation 44 (CD44) in CRC to be associated with cancer progression, stemness, resistance to therapy, metastasis, and poor clinical outcomes." (PMID 36672201, 2023). "The CD44 transmembrane receptor is multi-functional and varies based on exon splicing, widely associated with cell–cell interactions and migration with surface component cleavage in cancer migration." (PMID 36671668, 2023). "Therefore, the establishment and characterization of mAbs, which recognize each CD44v, are essential for understanding each variant function and development of CD44-targeting cancer therapy." (PMID 37185762, 2023). "CD44 has previously been linked to development, immune responses and cancer progression." (PMID 37100912, 2023). "The CD44 variant exon-containing isoforms (CD44v) are overexpressed in carcinomas." (PMID 36835416, 2023). "Fluorescence-activated cell sorting (FACS) using CD44 and CD24 as markers revealed that HMLE-EMT cultures likewise contained a distinct subpopulation of cells carrying the CD44+CD24low/− antigenic phenotype associated with so-called mesenchymal cancer stem cells (CSC)." (PMID 36551699, 2022). "Additionally, in MCF-7 cells, SETD7 knockdown induced the purported cancer stem-like cell phenotype (CD44+/CD24−/low) and dedifferentiation of mammospheres associated with loss of cadherin-1." (PMID 35326563, 2022). "The CD44 variant (CD44v) isoform, CD44v8-10, is known to bind and to stabilize the cystine transporter subunit (xCT), producing reduced glutathione, thereby enhancing the antioxidant defense of cancer stem cells." (PMID 35130955, 2022).
cancer (continued). "CD44 is a cancer stem cell marker that is expressed at high levels during tumorigenesis and in epithelial cells; it is associated with a poor clinical prognosis and cancer metastasis." (PMID 35093120, 2022). "The biological role of CD44 in cancer is intimately linked to the nature of protein isoforms 85 that, in the absence of dedicated analytical workflows, have been inferred from transcripts analysis complemented with immunoassays, lacking the necessary specificity for isoform distinction." (PMID 35547758, 2022). "Hence, the discovery of the differential expression of CD44 variants in cancer biology explained the role of variant 6 in the metastatic processes of rat tumors." (PMID 35346305, 2022). "Elevated CD44 is linked to EMT-related mesenchymal cancer cell phenotypes and to increased levels of several mesenchymal markers, as well as high grade of PDAC, including via the activation Akt pathway, which targets E-cadherin expression and thus generates EMT." (PMID 35163198, 2022). "Hence the evolution of CD44 expression and its associated cost in terms of cancer malignancy would be likely a case of antagonistic pleiotropy, where positive selection in early life stage is associated with disease burden in older age." (PMID 36148042, 2022). "Thus, SSC tumors cells express alternative isoforms of CD44, associated with enhanced cell growth and cancer development." (PMID 35572966, 2022). "CD44 gene rs13347 polymorphism is significantly associated with elevated cancer risk in Asians." (PMID 36611698, 2022). "Furthermore, other CD44 variant exons, such as CD44v6 and CD44v9, have also been described to confer chemotherapeutic resistance to cancer cells through the regulation of redox balance." (PMID 36243113, 2022). "CD44 has several variant isoforms generated through alternative mRNA splicing and these isoforms are reported to be associated with higher metastatic potential and poorer prognosis in various cancers, including CRC." (PMID 35172821, 2022). "CD44 is an extracellular matrix receptor implicated in cancer progression." (PMID 36148042, 2022). "Notably, we observed that silencing CBFB in MDA-MB-436 cells resulted in the reduced expression of EMT regulator Snail, metastasis/cancer stem cell marker CD44, and bone metastasis–associated markers OPN and Runx2." (PMID 35903297, 2022). "Moreover, the increased expression of cancer stem cell markers, such as CD44 and its variants (CD44v6 and CD44v8-10), was also correlated with short RFS and poor prognosis." (PMID 35757604, 2022). "Higher CD44 expression causes higher stromal invasibility of fibroblast populations by cancer cells, and may thus, in part, explain the high vulnerability of humans to malignancies of the skin compared to that of bovines and horses." (PMID 36148042, 2022). "CD44 and its multiple splice variants are involved in a variety of cancer mechanisms, including angiogenesis via the ERM-VEGFR axis, cell proliferation via the ERM-VEGFR-MAPK axis, metabolic shift in cancer cells via the SRC-AKT axis, and cancer cell invasion via the HGF-MET-PI3K-AKT axis." (PMID 34570764, 2021). "In TNBC, CD44 + /CD24- phenotypes are associated with cancer stem cells." (PMID 33413403, 2021). "CD44 was the first cell surface receptor to be functionally associated with cancer metastasis." (PMID 34070790, 2021). "Interestingly, CD44 variants’ (i.e., CD44v and CD44s) expression in cancer have been reported as markers for poor prognosis and regulators of EMT and plasticity of cancer cells." (PMID 34360868, 2021). "Decreased expression of the tumorigenic CD44 may be one mechanism by which smoking cessation lowers cancer risk." (PMID 34948786, 2021).
cancer (continued). "CD44 may be a cancer cell-associated ligand for Siglec-15, due to CD44 is overexpressed in various types of solid tumors." (PMID 34943606, 2021). "Anti-CD44 monoclonal antibodies (mAbs) have been shown to block the formation of subcutaneous tumors and to repress metastasis in mice, and down regulation of CD44 in cancer cells has been shown to reduce stem cell-associated traits." (PMID 33891595, 2021). "However, inflammation and cancer prevail over the expression of CD44 variants deriving from splicing events." (PMID 34360868, 2021). "Interestingly, these markers also correlated with the expression of the cancer stem cell marker CD44, which is associated with chemoresistance and decreased E-cadherin, an epithelial marker." (PMID 34571860, 2021). "Components of the TGFβ signaling cascade, including its receptors and downstream target genes, are highly expressed in ER- breast tumors, enriched in CD44+/CD24−/low cancer stem cells, and their expression is associated with a significant shortening of distant metastasis-free survival outcome." (PMID 33649296, 2021). "Additionally, HA induces the invasive behavior of cancer cells themselves and causes increased hydration and interstitial pressure via CD44, which promotes fibroblast penetration as well as the migration and invasion activity of cancer cells." (PMID 33968752, 2021). "Thus, targeting HA, CD44 (variant and standard) isoform, and HA-CD44 binding consider as an attractive and useful approach towards cancer therapeutics." (PMID 34513617, 2021). "The targeting of CD44 variants with MAbs could be a novel immunotherapy for cancer treatment, and CD44v3 may be a potential target for CAR T cell therapy for metastatic melanoma." (PMID 34207884, 2021). "Considering that increased levels of soluble CD44 can be associated with MM patient decreased survival, its over-expression on MM EV surface with respect to healthy subjects highlights the considerable role of this antigen as hallmark of cancer EVs." (PMID 33299143, 2021). "CD44 is a stemness marker associated with cancer metastatic progression." (PMID 32204402, 2020). "However, the underlying molecular mechanism regarding CD44 cross-linking during cancer cell metastasis is poorly understood." (PMID 33292278, 2020). "While the CD44 splicing variants have been described to be involved in cancer progression and development, the regulatory mechanism(s) underlying their production remain unclear." (PMID 33143085, 2020). "For example, CD44, an important adhesion molecule serving a critical role in cancer development, has been demonstrated to be associated with risk for several types of cancer via its different splicing modes and contains 3 types splicing modes in GC (AA, AT, and ES)." (PMID 33281863, 2020). "The abnormal expression of CD44 splice variants is associated with treatment refractoriness, recurrence, and prognosis, and overexpression of both CD44s and variants serves a long list of biological functions across many cancer types." (PMID 32984308, 2020). "However, the fact that CD44 is correlated with poor prognosis suggested that it is more linked with cancer progression and metastasis." (PMID 33372595, 2020). "Because studies suggest that interactions between low molecular mass HA and CD44 may play a role in cancer-associated inflammation, we investigated whether HA fragmentation occurs within the Hs578T and MDA-MB-231 cells." (PMID 32455980, 2020). "Moreover, immunohistochemistry analysis of lung metastasis nodules revealed the increased expression of two cancer‐associated fibroblast (CAF) markers CD44 and PDGFRβ, in vec‐sEVs pre‐conditioning lung metastasis nodules." (PMID 33304474, 2020). "CD44 has also been implicated as a CSC marker in human cancers." (PMID 32434417, 2020).